IL10 (interleukin 10)
Diseases named in the same sentence as IL10 in open-access papers (continued):
Sharing a sentence is not in itself a finding about the gene and the disease.
gastric cancer (continued). "The correlation between immune checkpoint gene expression and IL-10, TGF-β1 levels in gastric cancer." (PMID 41438510, 2025). "In a gastric cancer mouse model, CCR8 blockade downregulated Treg-produced IL-10 and reversed the suppression by Tregs on the secretion and proliferation of CD8+ T cells." (PMID 40186298, 2025). "IL-10 expression showed a positive correlation with TGF-β1 (Spearman r > 0.5), indicating potential transcriptional co-regulation in gastric cancer." (PMID 41438510, 2025). "In gastric cancer, tumor-infiltrated Tregs with higher expression of CCR8 produce more IL-10 molecules in vitro." (PMID 40186298, 2025). "This combined therapy downregulates Foxp3, IL-10, and TGF-β1 expression, reduces Treg proportions in peripheral blood, and modulates the immunosuppressive microenvironment of gastric cancer." (PMID 41438510, 2025). "Professor Chang-Ming Huang and colleagues confirmed that in gastric cancer, CDK5RAP3 inhibited nuclear transcription of NF-κB, thereby decreasing the secretion of cytokines IL4 and IL10 and blocking the polarization of M2 macrophages." (PMID 38643190, 2024). "An enrichment of IL10+ CD19+CD24hiCD38hi Bregs promoting the conversion of effector T cells into Foxp3+ Tregs in vitro was identified in breast and gastric cancer patients." (PMID 39346706, 2024). "Through IL-10 secretion and cellular contact mechanisms, CD45RA−CCR7+ Tregs exhibit strong inhibitory effects on CD8+ T cells, thereby promoting the growth of gastric cancer." (PMID 39840050, 2024). "This pathway directly promotes the expression of gastric cancer-derived IL-10 and forms a positive feedback loop that further releases macrophage-derived CXCL8 under the IL-10/NF-κB/CXCL8 axis." (PMID 39199574, 2024). "In contrast, the levels of IL4 and IL10 in the culture supernatant increased significantly in CDK5RAP3-depleted gastric cancer cells, while PDTC reduced the upregulation of IL4 and IL10 levels induced by gastric cancer cells with low CDK5RAP3 expression." (PMID 35999359, 2023). "Interestingly, the IL10+ Treg cluster also expressed high levels of PTMS, ZNF282, and TP63, which have been associated with oncogene activity and might help explain the association of H. pylori infection with the development of gastric cancer." (PMID 36810249, 2023). "We identified that IL4 and IL10 were significantly enriched in the KEGG ‘cytokine-cytokine receptor interaction pathway’, which is significantly activated in gastric cancer with low CDK5RAP3 expression." (PMID 35999359, 2023). "Stomach-cancer-derived exosomes can induce PD1+ TAM generation and these cells can produce a large amount of IL-10, impair CD8+ T-cell function, and create conditions to promote stomach-cancer progression." (PMID 35382168, 2022). "Promote the secretion of IL-6, IL-10, and VEGF, leading to immature differentiation of DCs and induction of gastric cancer." (PMID 36314013, 2022). "In patients with gastric cancer, exosomal TNF-α and TGF-β levels were increased, whereas the IL-10 level was decreased." (PMID 33803292, 2021). "We found that production of the cytokines tested (IL-2, IL-4, IL-6, IL-10, IFN-γ) were up-regulated after exposure to gastric cancer derived exosomes." (PMID 32901082, 2020). "IL-10-expressing CD24+CD38+ Bregs were characterized in gastric cancer (GC) patients." (PMID 33193391, 2020). "RT-qPCR results also showed higher levels of CD163, CD204, CD206, IL-10, and CCL-22 mRNA in peripheral blood-derived macrophages selected from gastric cancer patients than from healthy controls." (PMID 31801938, 2019). "IFN-γ and IL-10 levels were significantly higher in early (I/II) and late stage (III/IV) gastric cancer; IL-1β and IL-8 were higher and MCP-1 was lower only in late stage (IV) patients." (PMID 28558708, 2017).
gastric cancer (continued). "IFN-γ and IL-10 were significantly higher in both intestinal and diffuse gastric cancer, whereas IL-1β and IL-6 were higher and TGF-β lower only in intestinal gastric cancer; MCP-1 was lower only in diffuse gastric cancer." (PMID 28558708, 2017). "Levels of IL-1β, IL-6, IFN-γ, and IL-10 were significantly higher and that of MCP-1 was lower in gastric cancer patients compared with controls." (PMID 28558708, 2017). "We also included the interleukin-10 gene (IL-10) and cyclooxygenase-2 gene (COX-2), both of which participate in chronic inflammation and have been reported to affect gastric cancer outcomes after H. pylori infection." (PMID 25884934, 2015). "In the present study, we observed the levels of IL-6, IL-10 and VEGF in serum were significant decreased after removal of gastric cancer." (PMID 24116074, 2013). "Previous studies showed that lentinan elicited peritoneal macrophages with increased secretion of IL-12 in vitro and reduced IL-10 in vivo and enhanced the production of IL-1β and TNF-α in peripheral monocytes from the patients with gastric carcinoma." (PMID 24223225, 2013). "Compared with the normal control rats, blood IL-2, IL-4, IL-10 and TNF-α levels were significantly reduced in the gastric cancer model rats, while blood IL-6 level was significantly increased." (PMID 21686188, 2011). "In this study, blood IL-2, IL-4, IL-10 and TNF-α levels in gastric cancer model control rats were significantly lower than those in normal control rats." (PMID 21686188, 2011). "Lycopene treatment had significantly increased blood IL-2, IL-4, IL-10, TNF-α levels and reduced the IL-6 level in gastric cancer rats." (PMID 21686188, 2011). "Recent studies reveal that certain cytokines in TME, such as IL-10 and IFN-γ, may affect the treatment outcomes because the high levels of antitumor cytokines are related to better survival rates in patients with gastric cancer." (PMID 40309351, 2025). "This indicates that in the gastric cancer microenvironment, Tregs-related molecules (FOXP3) and immune suppressive factors (IL10, TGF-β1), as well as checkpoint molecules (CTLA4), are highly expressed and enriched, jointly shaping an immunosuppressive microenvironment." (PMID 41438510, 2025). "In summary, elevated IL-10 and TGF-β1 levels in gastric cancer synergistically enhance immune checkpoint gene expression, including CD274 and CTLA4, thereby strengthening the immunosuppressive microenvironment and informing immune therapy resistance mechanisms and combined targeted strategies." (PMID 41438510, 2025). "Foxp3 showed a positive correlation with IL-10 and TGF-β1 (r ≈ 0.5), suggesting that these immune-suppressive molecules exhibit consistent expression patterns and collectively influence the immune microenvironment in gastric cancer." (PMID 41438510, 2025). "Actually, IL-10 increases CD8 T cell infiltration and IFN-γ production, and favors effective T cell memory responses, therefore, IL-10 may in gastric cancer be effective as an immunotherapy by potentiating the activity of antitumor CD8 T cells." (PMID 38444674, 2024). "Further exploration revealed that IL-10 may trigger the activation of the c-MET/STAT3 signaling pathway, fueling gastric cancer progression." (PMID 39664377, 2024). "We observed that 5-FU-resistant gastric cancer cells were more effective than 5-FU-sensitive gastric cancer cells in skewing macrophages to M2 polarization, characterized by up-regulated expression of CD163, CD206, IL-10, Arg-1 and VEGF-A and down-regulated expression of CD86, TNF-α and IL-12." (PMID 36151545, 2022). "Furthermore, the levels of IL-6, IL-10, TNF-α, and VEGF in the gastric cancer cell line were higher than those in normal human gastric mucosal epithelial cells." (PMID 36618075, 2022). "In relation to gastric cancer, interleukin-6, 8, 10, 17A, TNF, and IFN-γ may have pro-tumour properties, although interleukin-10, TNF, and IFN-γ may have anti-tumour effects." (PMID 34944729, 2021).
gastric cancer (continued). "Quantification of circulating IL-4, TNF-α, IL-10 and INF-γ level in 17 patients diagnosed with gastric carcinoma and 30 subjects as control population was achieved by ELISA assay (Affymetrix Ebioscience, USA) using a calibration curve with known concentration standard (as described)." (PMID 30526523, 2018). "In gastric cancer patients, IL-10+ Bregs were more prevalent in tumor tissues versus non-tumoral tissues and peripheral blood." (PMID 27437104, 2016). "Moreover, IL-6 and STAT3 downstream signals such as IL-10 and VEGF were reduced in patients after removal of gastric cancer as compared to pre-operation." (PMID 24116074, 2013). "Comparison of serum cytokine levels of IL-6,IL-10 and VEGF in gastric cancer patients." (PMID 24116074, 2013). "Gastric cancer may partly result from the immunosuppressive status in the TME mediated by negative immune cells such as Tregs or M2 macrophages, and immune inhibitory cytokines such as IL-10 and TGF-β." (PMID 40244064, 2025). "In addition, 15×19 CAR T cells did not produce IL-4, IL-10, or IL-17A cytokines upon stimulation by gastric cancer cells." (PMID 36618357, 2022). "Inhibitory effect of endostar combined with radiotherapy on gastric cancer (GC) animal models and its effect on transforming growth factor-β1 (TGF-β1) and inter-leukin-10 (IL-10) were evaluated." (PMID 32669133, 2020). "However, one meta-analysis identified serum IL-10 as a negative prognostic marker in several gastrointestinal malignancies including colon and gastric cancers." (PMID 32298379, 2020). "Interestingly, MDDCs from gastric cancer patients revealed no significant IL-10 production after H. pylori stimulation." (PMID 22526791, 2012). "We speculate that immature DCs in gastric cancer patients do not produce sufficient IL-10." (PMID 22526791, 2012). "Similar to our results, a gastric cancer study found that neither G-CSF, GM-CSF, TGF-β, M-CSF, IL-1β, IL17A, IL-6, TNFα, IL10, IFNγ and IL22 were able to induce MC degranulation, while only adrenomedullin did." (PMID 32722549, 2020).
Hypertension (144 papers, 2007 to 2026). The presence of chronic increased pressure in the systemic arterial system. "For example, IL-10 ameliorates hypertension-induced renal and vascular injury, and genetic polymorphisms in IL-10 are also protective against diabetic nephropathy." (PMID 38545112, 2024). "We give specific introduction to recent findings of MCP-1, IL-6, TNF-β and IL-10 in hypertension and show underlying effect in the pathogenesis of effects on kidney, cardiovascular and other tissues." (PMID 36195874, 2022). "Mice deficient in IL-10 develop similar degrees of hypertension but more severe endothelial dysfunction associated with an increased superoxide production during Ang II treatment." (PMID 33394136, 2021). "Before we conducted MR analysis, we identified an invalid variant rs7088799, which was an instrument variant of IL-10 and IL-12p70, and also associated with body mass index, blood pressure, and hypertension (p < 5 × 10–6) using PhenoScanner V2." (PMID 35111052, 2021). "The increase of inflammatory cytokines (TNF-α, IL-2, IL-6 and IL-10) in the serum indicates an increase of systemic inflammation and a risk of hypertension for the mercury-exposed population." (PMID 33083327, 2020). "IL10 (interleukin 10, ~49 Kb upstream of rs3813963) has been associated with hypertension and with alcoholic cirrhosis." (PMID 29912962, 2018). "The analysis of the genotype frequencies revealed the association of hypertension with the CC genotype and C allele for IL-10 -592C/A polymorphism (p = 0.013, OR 9.400, and CI 95% 1.509–58.568 and p = 0.009, OR 3.830, and CI 95% 1.206–12.546, resp)." (PMID 26064986, 2015). "Those genes involved in IL10-induced signal transductions were associated with inflammatory diseases and ischemic stroke with hypertension." (PMID 25603303, 2015). "Hypertension was associated with the CC genotype and C allele for IL-10 -592C/A polymorphism (p = 0.013 and p = 0.009) and higher frequencies of T (p = 0.047) and C (p = 0.033) alleles of the TGF-β1 codon 10T/C and IL-10 -819T/C polymorphisms, respectively." (PMID 26064986, 2015). "A higher frequency of T allele for the TGF-β1 codon 10T/C (p = 0.047, OR 2.810, and CI 95% 1.890–9.148) and C allele for the IL-10 −819T/C (p = 0.033, OR 0.338, and CI 95% 1.107–1.154) was also observed in patients with hypertension." (PMID 26064986, 2015). "DNA variants in IL10rb, a subunit of IL10R, have been associated with ischemic stroke in individuals with hypertension, and IL10 deficiency has been associated with preeclampsia, a condition characterised by high blood pressure during pregnancy." (PMID 25259444, 2014). "A recent study on an experimental rat hypertension model revealed the normalization of blood pressure levels and endothelial function in association with IL-10 administration." (PMID 22462002, 2012). "Overexpression of IL-10 in the brain (particularly within the PVN) ameliorates hypertension and associated organ damage in hypertensive rats." (PMID 23285093, 2012). "The primary aim of this research was to explore whether treatment with recombinant IL-10 affects both blood pressure and vascular remodelling in hypertension caused by Ang II." (PMID 35528508, 2022). "In our study we found an association between the CC genotype and C allele for IL-10 -592C/A polymorphism and hypertension; furthermore we found a trend for association of the same polymorphism and BMI groups, since the -592AA genotype was less frequent in the obese T2D patients." (PMID 26064986, 2015). "In addition, we observed an association of the C allele for the IL-10 -819T/C polymorphism and patients with hypertension." (PMID 26064986, 2015). "Since IL-10 -592C/A polymorphism showed an association and a tendency for association with hypertension and BMI groups, respectively, an analysis of haplotype frequencies for IL-10 polymorphisms (-1082G/A, -819T/C, and -512C/A) was performed in the patients grouped according to T2D comorbidities." (PMID 26064986, 2015).
Hypertension (continued). "A reduction in endogenous IL‐10 production has been recently linked to the development of angiotensin II (ANG II)‐induced hypertension and inflammation in mice which can be partially attenuated by replacement of T‐regulatory (Treg) cells, a common source of IL‐10 production." (PMID 24744897, 2014). "Thus, a low expression of IL-10 has been related to the polymorphisms in the IL-10 gene (−1082 A/G, −819 T/C and −592 A/C) in patients with hypertension, myocardial infarction and coronary artery disease.TGF-β is a cytokine widely distributed throughout the body." (PMID 31816847, 2019). "Several animal model studies have shown an advantageous effect of IL‐10 administration in pregnancy‐induced hypertension." (PMID 41369322, 2025). "However, the observed positive association between IL-10 and bSBP only in the blood pressure risk group might represent a paradoxical compensatory anti-inflammatory response to counteract inflammation associated with high blood pressure." (PMID 41094183, 2025). "The administration of IL-10 reversed hypoxia-induced hypertension, proteinuria, and growth restriction in IL-10-depleted mice models." (PMID 38732104, 2024). "Regarding the reduction in IL‐10 serum levels in the SHR group in comparison to WKY, this is consistent with decreased plasma IL‐10 levels documented in patients with coronary artery disease and hypertension, as well as in various arterial hypertension models." (PMID 38504425, 2024). "Using an anti-inflammatory agent or overexpression of interleukin-10 in the brain attenuates hypertension." (PMID 36899953, 2023). "Hypertension was associated with increased levels of both pro-inflammatory (CCL3) and anti-inflammatory (IL-10) cytokines." (PMID 36769452, 2023). "Differences in IL-10 concentrations in the OSA patients in relation to the presence of hypertension were found, with lower IL-10 concentrations in hypertensive than in normotensive patients." (PMID 36769452, 2023). "Our findings are in agreement with these reports, as serum levels of IL-6, IL-8, IL-10, TNFα were significantly elevated in patients with arterial hypertension." (PMID 37969879, 2023). "On the other hand, HIIT downregulated TNF-α and IL-6 and upregulated IL-10 expression, subsequently attenuating hypertension-induced inflammation." (PMID 36865350, 2023). "In summary, these studies support the anti-inflammatory effects of IL-10 in hypertension and vascular remodelling." (PMID 35528508, 2022). "Meanwhile, the systemic therapeutic effect of IL-10 on vascular dysfunction in hypertension and the molecular mechanism remain to be studied." (PMID 35528508, 2022). "As an anti-inflammatory factor, IL-10 has a significant impact on sympathetic outflow, BP and cardiac remodeling in experimental models of hypertension." (PMID 35250473, 2022). "Despite these observations, the role of IL-10 administration in the effect of vascular hypertrophy and remodelling in hypertension is not well understood." (PMID 35528508, 2022). "Taken as a whole, these results confirmed the protective role of IL-10 and its relieving effect on blood vessels and hypertension." (PMID 36195874, 2022). "Our results showed that IL-10 treatment reversed hypertension-induced vascular hypertrophy by decreasing aortic CSA and the M/L ratio." (PMID 35528508, 2022). "Activating NKTCs specifically with α-galactosylceramide or recombinant murine IL-10 improved Ang II-induced hypertension, cardiac function and unfavorable remodeling." (PMID 35354938, 2022). "The expression or secretion of MCP-1, IL-6, TGF-β and IL-10 are influenced by microbiota or its metabolite and have potential effect on hypertension." (PMID 36195874, 2022). "By employing qualitative model of biomolecular and cells like IFN-γ, IL-10, IL-17 and Th17 cells, scientists have put forward a brain-gut-bone marrow axis to illuminate the regulatory network of hypertension on a comprehensive scale." (PMID 36195874, 2022).